CD4 (CD4 molecule)
Diseases named in the same sentence as CD4 in open-access papers (continued):
Sharing a sentence is not in itself a finding about the gene and the disease.
tumor (continued). "However, it is not difficult to speculate that CD4+ T cells, CD8+ T cells, and other immune cells could be recruited by tumor cells and exert an immunosuppressive effect on tumor progression." (PMID 34257557, 2021). "Additionally, CD8 but not CD4 T cell numbers (represented as z-scores to normalize the numbers across experiments) were significantly increased in the anti-HVEM-treated group relative to the control group, suggesting a role for CD8+ T cells in tumor control." (PMID 34208480, 2021). "However, CD4+ T cells have gained attention in the field, as they are not only essential to promote help to CD8+ T cells, but are also able to kill tumor cells directly (via MHC-class II dependent recognition) or indirectly (e.g., via the activation of other immune cells like macrophages)." (PMID 33546283, 2021). "In a previous report, the peripheral CD4+/CD8+ T cell ratio was significantly lower in patients with HCC prior to TACE than in healthy volunteers and was increased 1 month after TACE, although its effect on anti-tumor immunity was not investigated in those studies." (PMID 34575463, 2021). "In addition, FATS deficiency promotes M1 polarization by stimulating and prolonging NF-κB activation by disrupting NF-κB/IκBα negative feedback loops and indirectly enhances both CD4+ T helper type 1 (Th1) and cytotoxic T lymphocyte (CTL) adaptive immune responses to promote tumor regression." (PMID 34262035, 2021). "The expression level of BID was negatively correlated with tumor purity and the infiltration levels of B cells and has significant positive correlations with CD8+ T cells, dendritic cells, macrophages, and neutrophil, but not with the infiltration levels of CD4+ T cells." (PMID 34868460, 2021). "Eight other immune subsets, including naive CD4+ T cells, Lag-3+/−CD8+ T cells and CD14+macrophages, showed no significant enrichment in neither tumour groups, although CD27− B cells with unknown functions were also significantly enriched in tumours with low immune-ITH." (PMID 33431814, 2021). "Adding the induced Treg by tumor explants with or without anti-PD-1 or/and anti-IL-21 treatment strongly inhibited the proliferation of responder T cells (both CD4 and CD8), reduced the IFN-γ, IL-2 levels of CD4+ T cells, and cytotoxicity, GranzymeB, Perforin levels of CD8+ T cells." (PMID 34026621, 2021). "Moreover, the tumor as well as the adjacent, nontumoral tissue displayed the increased presence of T cells featuring the Trm markers CD69 and CD103 (CD8+ C6, C7, and C8) or CD69 only (CD4+ C1 and C7), hereafter referred to as Trm." (PMID 34552178, 2021). "Moreover, we observed significant elevation of tumor-infiltrating CD3+, CD4+, and CD8 + T cells but not CD11B + myloid cells in mice administered combination therapy, suggesting that strategies co-blocking MET and PD-L1 synergistically potentiate anti-tumor immunity in mice." (PMID 34479614, 2021). "The decline in the CD4+ T cell count might be explained by the sequestration of lymphocytes to the growing tumor, or by a lack of continuing T-cell recovery, which might result in a lack of EBV-specific CD4+ T cells, which are important for the immune surveillance of EBV-infection." (PMID 33865435, 2021). "Interestingly, while a significant reduction of the tumor mass was observed, the authors could not evidence any increase of CD45+, CD3+/CD4+, and CD3+/CD8+ infiltrating cells in the whole tumor." (PMID 33916641, 2021). "Notably, our results showed that despite the high frequency of IFN-γ+CD4+ T cells in the tumor tissues, the frequency of IFN-γ+CD4+ T cells was not considerably different between the tumor and adjacent non-tumor tissues (26.2 ± 4.2% vs. 22.8 ± 4.8%, respectively, P > 0.05)." (PMID 34026621, 2021).
tumor (continued). "In murine models of surgical implantation of TLR agonist-loaded gels into tumor resection sites, they observed no local tumor recurrence for at least one month and significantly improved survival, with the efficacy dependent on type I IFN signaling, NK cells, and CD4 and CD8 T cells." (PMID 34058283, 2021). "Cytotoxic CD4+ T cells also express GNLY, which has a documented role in anti-microbial immunity; although a proven role in anti-tumor responses has not been documented, profiling of single-cell clones with cytotoxic activity pointed to an enrichment of GNLY expression in this population." (PMID 34910940, 2021). "Interestingly, EVs isolated from irradiated tumour cells (H22 cells and 4T1 cells; 8 Gy) in vitro were shown to have immunomodulatory effects when mice were inoculated in vivo, enhancing CD8+ and CD4+ T-cell infiltration in lung metastasis in comparison to nonirradiated EVs." (PMID 33467153, 2021). "Importantly, strong negative correlations were detected between the numbers of neutrophils and those of CD4+CD8+ cells in the TMEs of both subtypes of NSCLC, but not in non-adjacent lung tissue, while PD-1-expressing CD4+ T cells correlated with tumor size and clinical stage." (PMID 34168563, 2021). "However, since the percentage of CD4+ T cells in the INT and IT groups was not significantly different, the presence of CD4+ T cells in the tumor areas may not always indicate tumor elimination; instead, they may indicate tumor progression." (PMID 34164110, 2021). "Indeed, CD4 Treg cells were present at a high frequency (>40% of CD4 T cells) and number in treatment-naive 005GSC and GL261-MGH tumors, but were absent in sections from tumor-free brain tissues." (PMID 33976133, 2021). "Among these activities we find the ability to modulate the non-specific and innate immune functions of NK cells, CD4+ and CD8+ T cells, and/or cytokine production inflammation, and apoptosis through multiple pathways that have been shown to lead to anti-tumor properties in vivo." (PMID 33114220, 2020). "In contrast, CD3+CD4+ T-lymphocytes, the most abundant lymphocytic infiltrating population, and CD3+CD8+ T-lymphocytes did not change between the different group of treatments, while B-lymphocytes were very low (always < 1.5% compared to total CD3+ T-lymphocytes) within tumor mass (data not shown)." (PMID 32155954, 2020). "Last but not least, immunosuppressive mechanisms in the tumor microenvironment (TME) other than the PD-L1/PD-1 and CTLA-4 pathways may render checkpoint blockade ineffective, such as inhibitory myeloid cell types and CD4+ T-regulatory cells." (PMID 32358491, 2020). "Finally, mice that completely suppressed tumor growth demonstrated no T cell response to TERT, either autoepitope TERT2 or CD4+ and CD8+ T cell epitopes represented by TERT1, TERT6, and TERT8, i.e., the rejection was not dependent on the adaptive immune response." (PMID 32570805, 2020). "V in CD4 T cells, which were both defined as dysfunctional populations in each T cell, were significantly upregulated in the patients with higher tumour grade (WHO/ISUP grades 3 and 4) (n = 29) rather than lower tumour grade (WHO/ISUP grades 1 and 2) (n = 68) (Fr." (PMID 32277125, 2020). "However, magnitude of the response expressed as populations of IFN-γ/IL-2/TNF-γ producing TERT6- and TERT8-specific CD4+ and CD8+ T cells showed no inverse correlation to the size of the rtTERT-expressing tumors (i.e., it was not a decisive factor in tumor rejection)." (PMID 32570805, 2020). "The intracellular expression of IFNγ in either CD4+ or CD8+ T cells remains unchanged between shScr-ST and shIDO-ST-treated groups, which may explain the lack of tumor control by sub-therapeutic doses of shIDO-ST alone." (PMID 33339195, 2020).
tumor (continued). "CD4+CD25+ Treg cells may play an immunosuppressive role by activating them after recognizing tumor antigens and inhibit the production of antitumor immune responses in the body, to leave the body in a state of low or no response to the tumor." (PMID 33204731, 2020). "Furthermore, mice rejecting tumors exhibited no CD4+ or CD8+ T response to TERT1, TERT6, or TERT8, indicating that T cell response against these epitopes was not a critical determinant of the restricted tumor growth." (PMID 32570805, 2020). "Furthermore, we found that IL-15 could induce human CD4+ T cells to develop memory phenotypes more easily than human CD8+ T cells, the induced memory CD4+ T cells could respond to DCs pulsed with tumor antigens (Data not shown)." (PMID 32221812, 2020). "To exert such a powerful prognostic influence on patient outcome, we explored the hypothesis that intra‐tumoral CD4+FOXP3+ T cells in GC interact with other nearby immune effector cells and exert their anti‐tumor effect indirectly rather than via direct tumor cell contact." (PMID 32377339, 2020). "Hence, although we detected the decreased numbers of Tregs, tumor-associated macrophages and tumor-associated neutrophils, and increased numbers of functional DCs, CD4+, and CD8+ T cells on day 3 after RFA treatment, the transient immune responses lacked the ability to suppress tumor growth." (PMID 32719347, 2020). "However, we identified neither correlations between frequencies of classical circulating CD4+ or CD8+ T-cells lacking CD56 expression, nor their PD-1+ fractions with outcome after therapy, although these populations may contain tumor-reactive cells." (PMID 31419253, 2019). "For example, interactions between CD4+ T cells and CD8+ T cells help determine the level of anti-tumor immunity, whereas the interaction between CD8+ PD1+ T cells and PD-L1+ target cells can lead to T cell exhaustion and reduction, if not outright abrogation, of anti-tumor activity." (PMID 30651131, 2019). "Notably, systemic CpG-C administration did not affect infiltration of T cells (i.e., CD4+) or monocytes (i.e., CD68+) into the brain, or the number of GFP+ cells (i.e., monocytes/microglia) evident in the brain 24 hours following administration of tumor cells." (PMID 30921319, 2019). "However, despite increases in cytokine-producing CD4 and CD8 T cells following erlotinib-treatment, combination treatment with immunotherapies like anti-PD-1 or a CD40 agonist did not effectively prevent tumor relapse." (PMID 31291990, 2019). "In summary, TAM homeostasis within the MC38 tumor microenvironment is maintained by production of CSF1, not IL34, and inhibition of signaling not only influenced the myeloid compartment but also inhibited CD4+ T cell accumulation, favoring a reduction in CD4+ FoxP3+ T cells." (PMID 31552020, 2019). "However, although potential rat IgG2a-specific CD4+ T cells could be induced in the vaccination procedure, these helper CD4+ T cells were not involved in the OVA-specific anti-tumor response." (PMID 30237798, 2018). "In contrast, there was little or no increase in the abundance of CD4+ or CD8+ T cells or NK cells in the spleens of the mice treated with pixatimod, anti PD-1 antibody or the combination when compared to the spleens of control mice indicating that the immune response was tumor-specific." (PMID 29898788, 2018). "In addition, unlike tumour‐specific CD8+ T cells, anti‐tumour CD4+ T cells may lack direct cytotoxic abilities." (PMID 27324616, 2017). "Strikingly, the anti-tumor effects mediated by doxycycline treatment were absent in immunocompromised nu/nu mice harboring CT26 tumors and in mice treated with depleting antibodies against CD8 and CD4, implying an essential contribution from the adaptive immune system to this anti-tumor response." (PMID 29246442, 2017).
tumor (continued). "Moreover, therapeutic outcome due to direct stimulation of tumor-specific effector CD4+ and CD8+ T cells by GITR agonist DTA-1 has been demonstrated in various vaccine - tumor models and adoptive transfer studies without affecting the Treg population and their function." (PMID 28807056, 2017). "Given that CD4+ but not CD8+ T cells appear necessary for combination therapy and that only tumor-specific CD4+ T cells could be detected, we decided to investigate whether T-cell priming during therapy was critical for protection from tumor rechallenge." (PMID 27890931, 2017). "However, these previous results are not conclusive, since tumor cells under certain circumstances, such as inflammation, may show expression of MHC class II, and thus be subject to direct killing by CD4+ T cells." (PMID 27626487, 2016). "In contrast, the percentage of CD8+ T cells was relatively comparable (ratio~1.0) to that of CD4+ T cells in the spleen or draining lymph node (DLN) of wt B6 recipients inoculated with tumors (spleen-TR or DLN-TR), or even lower in the spleen of wt B6 mice without tumor inoculation (WtB6 Spl)." (PMID 27835902, 2016). "IEC isolated from patients with non neoplastic disease provoked an increase in the proportion of activated CD8+CD38+ T-cell that was significantly blocked by the addition of anti-CD80 antibody, whereas no significant changes were observed in terms of CD4 activation." (PMID 25595911, 2015). "However, it is reasonable, that in the absence of Tregs, CD4+ T cells might activate tumor-resident DCs through CD40L–CD40 interaction, which then can efficiently present tumor antigen and promote T cell activation." (PMID 26483791, 2015). "AMHR2-CD vaccination significantly inhibited ID8 tumor growth when administered either prophylactically or therapeutically, and protection against EOC growth was passively transferred into naive recipients with AMHR2-CD-primed CD4+ T cells but not with primed B cells." (PMID 26618181, 2015). "In addition, expression of CD4 and CD8 lymphocytes was studied in a subset of 5 patients including CD70+ and CD70− biopsies, demonstrating an increased CD4/CD8 ratio in biopsies containing CD70+ tumor cells (data not shown)." (PMID 25951351, 2015). "In our study MB-FUS exposure facilitated a response of mostly conventional CD4+T cells with a moderate response by CD8+T cells, and no response by Treg cells, consistent with an antitumor function of conventional CD4+T cells as borne out by tumor growth inhibition." (PMID 23140567, 2012). "In BALB/c mice immunized with Her2MPtVLP, depletion of both, but not only either CD4+ or CD8+ cells was required to eliminate inhibition of tumour growth, irrespective of whether the anti-CD4 and/or anti-CD8 mAbs were delivered before immunization, or before tumour challenge." (PMID 20657846, 2010). "Moreover, looking at the whole T lymphocyte population with markers such as CD3 or even CD4 and CD8 knowing that these cell populations are also heterogeneous as they contain subpopulations with anti-tumor, but also tumor-promoting phenotypes might not provide accurate prognosis." (PMID 38887294, 2024). "Similarly, increased levels of adhesion molecules in circulating CD4+ T cells (CCR8, CD18) and monocytes (CD18, CCR8, Cd49f, CD54, LFA-3, P-selectin, CD29) were observed in baseline samples from patients whose tumor had pCR compared with those that did not have pCR." (PMID 38181044, 2024). "Nevertheless, an indirect CD4+ T cells killing mechanism, implying IFN-γ secretion and tumoricidal macrophages, has already been reviewed and could represent the way for MHC II-restricted T cells to eliminate tumor cells, without any MHC I-restricted CD8+ T cells involvement." (PMID 38545119, 2024).
tumor (continued). "This population negative for PD-1 within CD4 T cells and CD8 T cells exhibiting a TEM phenotype may represent a stem-cell like progenitor that after T cell activation remains active to generate new waves of effector T cells in response to the demand of a constant presence of tumor antigen." (PMID 37033927, 2023). "However, once the CAR-T cell is activated through the signaling CAR, which may be mediated through enhanced tumor cell binding by engaging CD4, the CAR-T cell can induce the killing of adjacent tumor cells lacking CD4, but expressing the desired tumor-specific antigen." (PMID 36059451, 2022). "However, the antitumor function of CD4+ T cells in the absence of CD8+ T cells has been reported in several studies, both preclinical and clinical, both for the treatment of primary tumors and rejection of tumor rechallenge in immune mice, in certain situations." (PMID 36159781, 2022). "Compared to those in the tumor-bearing control, ATRA treatment alone upregulated the levels of Th2 cells and Tregs, which suggested that ATRA treatment alone could not enhance the CD4+ T-cell-mediated antitumor immune response but could induce immunosuppression." (PMID 36389684, 2022). "However, for Hepa 1-6 tumor model, treatment with 100 mg/kg ART could decrease the percentages of MDSCs, G-MDSCs, and Treg cells but increased the percentages of CD3+, CD4+, and CD8+ T cells, while there was no change in the percentages of M-MDSCs compared to treatment with DMSO." (PMID 35785030, 2022). "Importantly, anti-CD4 mAb treatment-induced depletion of CD4+ T cells in vivo resulted in the elimination of tumor resistance in VISTA-KO mice treated with radiotherapy, whereas depletion of CD8+ T cells by the same mechanism had no impact on tumor growth or overall survival." (PMID 32600443, 2020). "Hence, while similar growing B16 and MC38 tumors show increases in CD8:CD4 T-cell ratio, only the MC38 tumor model shows reduced tumor growth, indicating that quantification of overarching immune subsets does not differentiate between responding and non-responding tumor models." (PMID 32690667, 2020). "To explore the possibility that endogenous CD4+ T cells are necessary for the improved antitumor response of m1928z-CD40L CAR T cell treatment, we took advantage of the finding that CD8+ CAR T cells alone, but not CD4+ CAR T cells, could cure A20.GL tumor-bearing mice." (PMID 33268774, 2020). "Furthermore, the molecular mechanism of CSF1/CSF1R in OSA remains unclear; the positive correlation with the expression of CSF1R and CD4/CD68 is not clear that it must play the positive effect on prognosis, and it may also be as a cancer promoting factor that involved in tumor immune escape." (PMID 32850346, 2020). "Similarly, systemic treatment of tumor-free mice with (R)-crizotinib, alone or in combination with CDDP, failed to affect the expression of these factors by splenic CD4+ and CD8+ T lymphocytes, neither affected those factors by lymph nodes’ CD4+ and CD8+ T lymphocytes (data not shown)." (PMID 30940805, 2019). "The fact that intratumoral cisplatin does not increase neither CD8+ nor CD4+ T cell infiltration and that the effect was abolished in NSG mice (lacking T cells but with reduced macrophage function) suggests that macrophages could be partially responsible for the anti-tumour effects." (PMID 30948731, 2019). "While class I HER2-DC1 enhanced only CD8+ T cell infiltration but not CD4+ T cells, class II HER2-DC1 vaccination induced both CD4 and CD8+ T cell infiltration, suggesting that vaccination with class II HER2-DC1 may be sufficient in generating anti-tumor immunity and HER2-specific immune responses." (PMID 31475002, 2019).